SIRT1 (sirtuin 1)
Diseases named in the same sentence as SIRT1 in open-access papers (continued):
Sharing a sentence is not in itself a finding about the gene and the disease.
Testicular torsion (2 papers, 2024). Testicular torsion is when the spermatic cord to a testicle twists, cutting off the blood supply. "Eprosartan hold promise for managing testicular dysfunction arising from testicular torsion exerting antioxidant, pro-autophagic and anti-apoptotic effect via the activation of SIRT1/Nrf2/HO-1 as well as Beclin-1/AMPK/mTOR pathways." (PMID 38822026, 2024).
thymic lymphoma (2 papers, 2011 to 2013).
thyroid tumor (2 papers, 2016 to 2023). A benign or malignant neoplasm affecting the thyroid gland. "Compared to normal thyroid tissue, thyroid tumors had lower expression of HIC1 and higher SIRT1 expression." (PMID 27793057, 2016).
uveal melanoma (2 papers, 2017 to 2022). A melanoma derived from melanocytes of the uveal tract.
vasculitis (2 papers, 2021 to 2024). "Considering the reported findings, it could be speculated that a declined SIRT1 expression in GCA patients might be linked to the observed oxidative stress and that these phenomena could have a role in the pathogenesis of this vasculitis, although further research is warranted to support this claim." (PMID 34073102, 2021).
ventricular septal defect (2 papers, 2018 to 2023). The presence of a defect (opening) in the septum that separates the two ventricles of the heart. "At this point, it is worth noting that an occurrence of single-nucleotide polymorphism (SNPs) at the Sirt1 promoter, which might alter Sirt1 expression, was found in human subjects with ventricular septal defects." (PMID 29497772, 2018).
xeroderma pigmentosum group A (2 papers, 2019 to 2022). Any xeroderma pigmentosum in which the cause of the disease is a mutation in the XPA gene. "Altered mitophagy due to SIRT1 decrease has also been demonstrated in Xeroderma pigmentosum group A (XPA) as well as ataxia-telangiectasia (AT) and Cockayne syndrome (CS), all associated with neurodegeneration and cancer." (PMID 31210843, 2019). "Indeed, PARP hyperactivation was shown to decrease activation of the NAD+‐ SIRT1‐PGC1α axis in cells from patients with Xeroderma Pigmentosum group A (XPA), a human disorder characterized by defective NER." (PMID 35834102, 2022).
Zika virus infection (2 papers, 2020 to 2025). "Interestingly, all of these have been found interacting with the sirtuin protein (SIRT1), and sirtuin inhibitors were reported to block Zika virus infection downstream of viral entry." (PMID 33133425, 2020).
Zinc deficiency (2 papers, 2019 to 2022). A deficiency of the essential metal Zinc; an essential cofactor for many enzymes. "Follow-up studies will elucidate the significance of the zinc deficiency-induced decrease in SIRT1 and mTOR protein levels on neuronal function." (PMID 35955944, 2022). "As a result, zinc deficiency down-regulates Sirt1 activity and Pgc-1α expression, which further affects Glut2 expression and mitochondrial function." (PMID 30324491, 2019).
Achalasia (1 paper, 2021). A disorder of esophageal motility characterized by the inability of the lower esophageal sphincter to relax during swallowing and by inadequate or lacking peristalsis in the lower half of the body of the esophagus. "The biological process of GO and KEGG assessments in this study demonstrated that phosphatase and tensin homolog (PTEN) and Sirtuin 1 (SIRT1) could be significant targets of miR-217 in the achalasia." (PMID 34377051, 2021).
acquired immunodeficiency syndrome (1 paper, 2023). "Sirt1 also contributes to the regulation of the amplification of human immunodeficiency virus 1 (HIV1), which infects CD4-carrying cells, in particular T helper cells, and thereby facilitates opportunistic infections and the development of acquired immunodeficiency syndrome (AIDS)." (PMID 37109478, 2023).
acute graft vs. host disease (1 paper, 2018). Graft-versus-host disease (GVHD) is a common complication following an allogeneic tissue transplant. "However, whether SIRT1 is involved in the progression of acute graft-vs.-host disease (aGVHD) has still remained unclear." (PMID 30622543, 2018).
acute leukemia (1 paper, 2022). A clonal (malignant) hematopoietic disorder with an acute onset, affecting the bone marrow and the peripheral blood. "Sirt1 loss also prevents the development of age-dependent B/myeloid mixed phenotype acute leukemia." (PMID 35484199, 2022).
advanced heart failure (1 paper, 2014). Patients with advanced heart failure have severe limitations, experiences symptoms even while at rest and are mostly bedbound patients. "In conclusion, in advanced heart failure, the changes associated with aging may be accelerated and the cardioprotective effect of Sirt1 is reduced due to the lower expression level and changes to downstream effector molecules." (PMID 24913149, 2014).
Age-related cataract (1 paper, 2019). A type of cataract (opacification of the lens) that forms during the course of aging. "In the human eye, expression of the SIRT1 gene was detected in the lens epithelium and in the retina of patients with senile cataract." (PMID 31287252, 2019). "However, the association of SIRT1 with age-related cataracts has not yet been fully elucidated." (PMID 31287252, 2019).
alcohol use disorder (1 paper, 2024). "An alternative role has been elucidated for SIRT1 in alcohol use disorder where increased SIRT1 expression, via dihydromyricetin and resveratrol, were protective against deleterious effects of alcohol in the liver and the brain." (PMID 39404407, 2024).
alcohol-related disorders (1 paper, 2017). Disorders related to or resulting from abuse or mis-use of alcohol. "Further research should to explore the SIRT1 gene function when ASP co-exists with alcohol-related disorders." (PMID 28439078, 2017).
anaplastic carcinoma (1 paper, 2023). "Similar to WB results, the cell lines that had a higher expression of SIRT1 protein were the CMT-U27 (simple ductal carcinoma) and P114 (anaplastic carcinoma) cell lines." (PMID 37627400, 2023).
aortic valve disease (1 paper, 2025). "SisselÅkra and colleagues further examined the expression of the senescencemarker sirtuin 1 (SIRT1) and nicotinamide phosphoribosyltransferas (NAMPT)enzyme, which regulates SIRT1 activity, in EAT, PAT, and SAT from CHD patients,using individuals with aortic valve disease as controls." (PMID 40160564, 2025).
aplastic anemia (1 paper, 2023). Anemia resulting from bone marrow failure (aplastic or hypoplastic bone marrow). "A clinical trial proved that the defective Sirt1 may be correlated to the abnormal IFNγ expression in severe aplastic anemia patients, and activation of Sirt1 signaling by SRT3025 may help improve the inflammatory status of severe aplastic anemia." (PMID 36843938, 2023).
ascending aortic aneurysm (1 paper, 2026). "The main aim of the study is toinvestigate the relationship of SIRT1 in ascending aortic aneurysms and type 1dissections." (PMID 41259217, 2026).
Ascites (1 paper, 2021). Accumulation of fluid in the peritoneal cavity (between the layers of the peritoneum that lines the abdomen). "Accordingly, this study comprehensively explores the impacts of intestinal SIRT1 deficiency on TNFα-mediated intestinal inflammation, intestinal barrier dysfunction, intestinal bacterial dysbiosis, bacterial translocation on the development of severe renal dysfunction in cirrhotic mice with ascites." (PMID 33513830, 2021).
atrioventricular block (1 paper, 2025). A heart block that is initiated in the atrioventricular node. "Furthermore, in an animal model of complete atrioventricular block, negative regulation of SIRT1 and LA fibrosis was observed in the LA myocardium." (PMID 39636756, 2025).
autoimmune encephalitis (1 paper, 2023). Inflammation of the brain secondary to an immune response triggered by the body itself. "Opposite results on the neuromodulatory potential of SIRT1 were obtained in a recent study on mice, in which in experimentally induced autoimmune encephalitis, the activation of SIRT1 had detrimental effects on reactive astrocytes, whereas SIRT1 inactivation produced anti-inflammatory effects." (PMID 37511397, 2023).
autoimmune uveitis (1 paper, 2019). An autoimmune form of uveitis (disease). "According to our results, KS23 may also act to ameliorate autoimmune uveitis via an anti-inflammatory response induced by the deacetylation of RELA/p65, following the upregulation of AMPK and SIRT1 expression." (PMID 31883532, 2019).
autosomal dominant polycystic kidney disease (1 paper, 2024). Autosomal dominant form of polycystic kidney disease. "Niacinamide has been shown to slow cyst growth and improve kidney function in two mouse models of autosomal dominant polycystic kidney disease (ADPKD), likely through SIRT-1 inhibition." (PMID 39339816, 2024).
Azoospermia (1 paper, 2025). Absence of any measurable level of sperm,whereby spermatozoa cannot be observed even after centrifugation of the semen pellet. "Our results provide preliminary evidence regarding the potential role of the NEAT1/miR-34a/SIRT1 axis, highlighting its possible relevance in understanding the molecular mechanisms underlying non-obstructive azoospermia and oligozoospermia." (PMID 40165339, 2025).
B-cell acute lymphoblastic leukemia (1 paper, 2024). A neoplasm of lymphoblasts committed to the B-cell lineage, typically composed of small to medium-sized blast cells. "Several transcription factors increase mTOR transcription including sirtuin 1 (SIRT1), myeloid zinc finger 1 (MZF1), and Nrf2 while Ikaros represses mTOR transcription in B cell acute lymphoblastic leukemia." (PMID 38270460, 2024).
Barth syndrome (1 paper, 2022). Barth syndrome (BTHS) is an inborn error of phospholipid metabolism characterized by dilated cardiomyopathy (DCM), skeletal myopathy, neutropenia, growth delay and organic aciduria. "Future work may help illuminate the dynamic interactions between the different NAD+ pools and SIRT1 activity in the context of Barth syndrome." (PMID 36107830, 2022).
bile duct cancer (1 paper, 2023). "We further showed that CCL3 promoted the metastasis of intrahepatic bile duct cancer cells by regulating VIRMA/SIRT1 pathway in the orthotopic ICC tumor model." (PMID 36691046, 2023).
Bladder Urothelial Carcinoma (1 paper, 2022). "A comparison with the cancer genome atlas TCGA reveals a downregulation of SIRT1 and MAT2B for several urogenital cancer entities like, Bladder Urothelial Carcinoma, Kidney renal papillary cell carcinoma, Kidney Chromophobe, Pan-kidney cohort (KICH+KIRC+KIRP)." (PMID 36170022, 2022).
blood pressure (1 paper, 2012). "The liaison between high blood pressure triggered by cardiac mIGF-1 transgene, downstream SIRT1 and improved memory of an aversive stimulus remains unclear." (PMID 22691943, 2012).
brain cancer (1 paper, 2018). A primary or metastatic malignant neoplasm affecting the brain. "In TCGA data set (183 brain cancer patients with cytogenetics information), the mRNA expression of SIRT1 was associated with cytogenetics risk category of patients, which was one of the most important prognostic factors in brain cancer." (PMID 29991742, 2018). "Kaplan–Meier analysis of revealed a positive correlation between the overall survival of patients and the mRNA expression of SIRT1 (P = 0.029), indicating the prognostic significance of SIRT1 in brain cancer." (PMID 29991742, 2018). "Brain cancer patients were clustered into the high-SIRT1 expression group (N = 36) and the low-SIRT1 expression group (N = 147)." (PMID 29991742, 2018). "We investigated the correlation between the expression level of SIRT1 and the clinical prognoses of brain cancer patients." (PMID 29991742, 2018). "Thus, in our study, we identified that SIRT1 was a key prognostic factor in brain cancer based upon The Cancer Genome Atlas and tissue microarray analyses." (PMID 29991742, 2018). "However, the applications of “SIRT1-modulating autophagy” in brain cancer remains in its infancy." (PMID 29991742, 2018).
brain inflammation (1 paper, 2023). "Second, recent data suggest that NAM n-oxide, which is mainly produced by the intestinal microbiota from NAM, behaves as a positive regulator of sirtuin 1 of herpes simplex virus-induced brain inflammation and microglial." (PMID 37513501, 2023).
cardia cancer (1 paper, 2021). A malignant neoplasm involving the cardia of stomach.
cerebral lesions (1 paper, 2025). "Indeed, silibinin might be considered to be a neuroprotective agent against cerebral lesions, through activation of the GAS6/Axl-SIRT1 pathways, improvement in mitochondrial function, reduction in oxidative stress and activation of apoptosis." (PMID 41441207, 2025).
Charcot-Marie-Tooth disease type 2K (1 paper, 2021). "The drastic reduction of SIRT1 may result from a mitochondrial complex I deficiency, as showed in Charcot-Marie-Tooth disease type 2K, or from failed mitochondrial/nuclear crosstalk in the absence of p43." (PMID 33526032, 2021).
cholelithiasis (1 paper, 2023). The presence of crystallized deposits forming in the gallbladder or biliary tree, primarily composed of cholesterol, bilirubin, and bile. "It increased the mRNA expression of AMPK, protein expression and phosphorylation level of AMPK, and protein expression of SIRT1 in the gallbladder tissues of the mice with cholelithiasis." (PMID 37641009, 2023). "Our study aims to investigate the possible molecular mechanism of AQP3 in regulating cholelithiasis, involved with regulating the AMPK/SIRT1 signaling pathway, in the hope of finding novel directions for repressing and treating cholelithiasis." (PMID 37641009, 2023). "Therefore, modulation of the AMPK/SIRT1 signaling pathway to ameliorate inflammatory injury may be one of the potential therapeutic tools to repress cholelithiasis." (PMID 37641009, 2023). "Moreover, the mRNA expression of SIRT1 and phosphorylation levels of SIRT1 and AMPK were significantly reduced in the gallbladder tissues of the mice with cholelithiasis relative to that in the normal control mice." (PMID 37641009, 2023).
chronic bronchitis (1 paper, 2024). A type of chronic obstructive pulmonary disease characterized by chronic inflammation in the bronchial tree that results in edema, mucus production, obstruction, and reduced airflow to and from the lung alveoli. "ADAM17 upregulation followed by SIRT1 suppression can lead to decreased ciliation, mucus hypersecretion, and attenuated MCC, a hallmark of chronic bronchitis in smokers and COPD." (PMID 39682757, 2024).
chronic lung disease (1 paper, 2025). According to the definitions of the American and British Thoracic Societies, including pulmonary functional tests, X-rays, and CT scans for items such as fibrosis, bronchiectasis, bullae, emphysema, nodular or lymphomatous abnormalities. "The reduction of SIRT1/6 in chronic lung diseases may accelerate lung aging by promoting cellular senescence." (PMID 40554265, 2025). "This has led to strategies to restore SIRT1/6 levels to normal, including chronic lung diseases." (PMID 40554265, 2025).
cleft palate (1 paper, 2026). Cleft palate is a fissure type embryopathy that affects the soft and hard palate to varying degrees. "In atRA-induced cleft palate models, SIRT1 suppression drives MSX1 hyperacetylation, accelerating proteasomal degradation and culminating in EPM apoptosis." (PMID 41856994, 2026).
cocaine addiction (1 paper, 2020). "Taken together, these findings suggest that SIRT1, an NAD-dependent enzyme, can influence molecular adaptations associated with cocaine addiction." (PMID 32423100, 2020). "This raises the possibility for the application of SIRT1 and SIRT2 inhibitors as potential agents to treat cocaine addiction." (PMID 32423100, 2020).
coenzyme Q10 deficiency (1 paper, 2023). A genetically heterogeneous condition, typically inherited in an autosomal recessive fashion, characterized by coenzyme Q10 deficiency. "Coenzyme Q10 deficiency has also been found to lower SIRT1 mRNA expression." (PMID 36979007, 2023).
colorectal adenoma (1 paper, 2025). An adenoma that arises from the colon or rectum. "We found that the key components of sirtuin pathway, Sirtuin 1 (Sirt1) and forkhead box O3 (FOXO3), are significantly associated with the YAP gene in promoting colorectal adenomas." (PMID 39977302, 2025).
congenital neutropenia (1 paper, 2019). "On the contrary, GM-CSF is not effective in congenital neutropenia because it is unable to activate iNAMPT upregulation and NAD/SIRT1 axis." (PMID 31402913, 2019).
coronary artery spasm (1 paper, 2022). "In addition, Sirt1-mediated NF-κB deacetylation hinders the myosin light-chain kinase/myosin light chain-2 (MLCK/MLC2) pathway and endothelin-1 (ET-1) expression, thus alleviating coronary artery spasm." (PMID 35387565, 2022).
coronary thrombosis (1 paper, 2021). Coagulation of blood in any of the coronary vessels. "Their study indicated that the miR33/SIRT1 pathway was involved in the increased pro-inflammatory and procoagulant status of coronary thrombosis in such patients." (PMID 34447791, 2021).
coxarthrosis (1 paper, 2025). "This pilot study aimed to investigate the effects of a cocktail with trolox, r-irisin and resveratrol on the metabolism of osteoblasts isolated from patients with coxarthrosis or fragility fracture by assessing the modulation of NOX4, SIRT1 and PTX3." (PMID 40956314, 2025).
Cutaneous T-cell lymphomas (1 paper, 2022). "Cutaneous T-cell lymphomas showed the increased expression of SIRT1." (PMID 36230534, 2022).
dermatitis (1 paper, 2024). An inflammatory process affecting the skin. "While SIRT1 levels in keratinocytes and dermal fibroblasts are upregulated, HDAC6 and CXCL13 levels are also upregulated to aggravate the inflammatory response of specific dermatitis, which is involved in the increased expression of Th1 and Th2 cytokines and the downregulation of Foxp3 and IL-10." (PMID 39081309, 2024).
dissection (1 paper, 2026). The separation and isolation of tissues for surgical purposes, or for the analysis or study of their structures. "The results showed that mortalitydue to aortic dissection, particularly in the thoracic region, increased by 70% inmice with SIRT1 destruction." (PMID 41259217, 2026).
dizziness (1 paper, 2014). A sensation of lightheadedness, unsteadiness, turning, spinning or rocking. "In this study, we confirmed that the blood SIRT1 level is attenuated in patients with chronic dizziness." (PMID 24624081, 2014).
DNA repair (1 paper, 2018). The process of restoring DNA after damage. "Increased NAD+ levels activate SIRT1's activity, and indeed, activating SIRT1 by adding nicotinamide riboside, an NAD+ precursor, improves the mitochondria quality via mitophagy induction and retards the progression of the DNA repair disorders." (PMID 30510631, 2018).
DNA repair disorders (1 paper, 2017). "Cells from these patients display mitochondrial dysfunctions related to SIRT1 (sirtuin 1) inhibition, a common mechanism for DNA repair disorders (XP-A and CS) with neurodegeneration." (PMID 29112132, 2017).